TIGIT (T cell immunoreceptor with Ig and ITIM domains)
Diseases named in the same sentence as TIGIT in open-access papers (continued):
Sharing a sentence is not in itself a finding about the gene and the disease.
tumor (continued). "The IC expression on NK-92 cells is comparable to the previously reported IC expression profile on tumour-infiltrating NK cells in other cancer entities with a DNAM-1 down-regulation and an upregulation of TIGIT." (PMID 40317320, 2025). "PD-L1 was positive in both tumor cells and in tumor-infiltrating cells, while CTLA-4, PD-1, PD-L1, TIM-3, TIGIT, and VISTA were mainly observed in tumor-infiltrating cells." (PMID 40565313, 2025). "Hemin, another small molecule that can interact with TIGIT/PVR, was developed based on virtual molecular docking and cell-based closure assays, and can interact with TIGIT/PVR and enhance anti-tumor CD8+ T cell killing activity." (PMID 40890162, 2025). "TIGIT, found on natural killer (NK) and T cells, interacts with CD155 on APCs and tumor cells to suppress immune responses." (PMID 40075754, 2025). "Aberrant expression of co-regulatory receptors including PD-1, TIGIT, and CD39 has been recently identified as sign of CD8+ T cell dysfunction in TILs of primary tumor tissue." (PMID 40274631, 2025). "TIGIT also binds, albeit with less affinity, to CD112, also known as Nectin-2, which is expressed on DCs, monocytes, and numerous tumor cell subtypes." (PMID 40075753, 2025). "Upregulation of LAG-3, TIM-3, TIGIT, and VISTA has been observed in patients with tumor recurrence after anti-PD-1/L1 or anti-CTLA-4 therapy, indicating the presence of an underlying mechanism of acquired resistance." (PMID 40075727, 2025). "In summary, immune checkpoint molecules such as TIGIT, LAG-3, and PD-1 hold significant promise for application in tumor immunotherapy." (PMID 40809844, 2025). "A recent report showed that a single CD-155/TIGIT (T cell immuno77receptor with Ig and ITIM domains) or PD-1/PD-L1 (Programmed death-1/Programmed death Ligand 1) blockade has limited anti-tumor effects." (PMID 41186893, 2025). "TIGIT has been reported as a marker of CD8+T cell failure and a characteristic marker of Tregs in the tumor microenvironment." (PMID 40356928, 2025). "TIGIT is expressed on the surface of various immune cells, including CD4+ T cells, CD8+ T cells, NK cells, regulatory T cells (Tregs), and tumor-infiltrating lymphocytes (TILs)." (PMID 40463500, 2025). "TIGIT efficiently obstructs costimulatory signals essential for activating effector T cells and NK cells by outcompeting CD226, thus diminishing anti-tumor immunity." (PMID 40567374, 2025). "Under the long-term stimulation of tumor antigens, some tumor-infiltrating lymphocytes will up-regulate the expression of some immunosuppressive receptors, such as PD-1, TIM3, LAG-3, and TIGIT." (PMID 40612858, 2025). "TIGIT (T cell immunoreceptor with Ig and ITIM domains) competes with the co-stimulatory receptor CD226 for binding to CD155, which is expressed in tumor cells and antigen-presenting cells." (PMID 39857682, 2025). "While the harvested tumor had SLL deposits, it resulted in a CD8+ predominant, tumor-reactive TIL product with an increased expression of LAG-3 and TIGIT." (PMID 41333460, 2025). "TIGIT binds to ligands CD155 and CD112, which are regulated by tumor cells and APCs in the tumor environment." (PMID 40584631, 2025). "TIGIT binds to two ligands, CD155 and CD112, that are expressed by tumor cells and antigen-presenting cells in the TME." (PMID 40565299, 2025). "PDL1 (CD274) - PD1 and TIGIT - CD155 (PVR) are common immune checkpoint pathways in tumors, through which tumor cells can inhibit the function of T cells by expressing CD274 and PVR." (PMID 40110547, 2025). "TIGIT binds to CD155, which is expressed on antigen-presenting cells or tumor cells, to suppress the functions of T cells." (PMID 40944710, 2025). "CITE−seq conjugates antibody bar−codes to capture cell−surface proteins alongside mRNA, providing a direct measure of PD−L1, TIM−3, TIGIT, and CTLA−4 abundance on tumour and immune subsets." (PMID 40959084, 2025).
tumor (continued). "In the TME, TIGIT and PD-1 synergistically inhibit the activity of CD226, thereby limiting the anti-tumor immune response of T cells." (PMID 40038799, 2025). "TIGIT, CD226, CD96 and PVRIG are expressed on T and NK cells, whereas CD155 (PVR) is often overexpressed on tumour cells." (PMID 41462864, 2025). "The identification of a TIGIT+PD-1+CXCL13+ CD8+ T cell subset—characterized by features of both function and tumor reactivity—highlights a critical population shaped by chronic antigen exposure and enriched particularly in MSI CRC patients." (PMID 40799645, 2025). "Dual targeting of LAG-3 and TIGIT or triple inhibition of LAG-3, PD-1, and Tim-3 reduces tumor growth." (PMID 40361336, 2025). "For the immune part, we focused on the TCR-mediated signaling pathway and major immune checkpoints including PD-1, PD-L1, CD28, CD80/CD86, LAG3, CTLA4, TIGIT, CD155, OX40, OX40L, 4-1BB, and 4-1BBL (expressed on T cells, tumor cells, or APCs)." (PMID 40276607, 2025). "TIGIT binds to CD155 on antigen-presenting cells and tumor cells, competing with the activating receptor 226 CD226." (PMID 40075661, 2025). "Other families of inhibitory receptors have been identified on NK cells, namely nectin receptors (TIGIT, CD96, and CD112R), which inhibit NK cell functions by binding to nectin molecules expressed on tumor cells." (PMID 40299429, 2025). "Together, TIGIT/PVRIG—CD112/CD155/PVRL4 signaling has recently shown to prevent T cell proliferation, tumor cell lysis, and the production of proinflammatory cytokines." (PMID 40274631, 2025). "In TNBC, the expression of TIGIT was shown on immune cells in TME and CD155 on tumor cells concomitantly with PD-1 and PD-L1 expression on immune and tumor cells, respectively, thus indicating the potential of therapeutic targeting of TIGIT in TNBC." (PMID 40003864, 2025). "There is growing evidence that TIGIT is highly expressed on TIL in different hematologic malignancies, leading to tumor progression and poor outcome." (PMID 41357215, 2025). "TIGIT interacts with CD155 (poliovirus receptor, PVR, or NECL-5) on the surface of antigen-presenting cells or tumor cells and inhibits the anti-tumor response of T cells and NK cells." (PMID 40510353, 2025). "CRISPR-Cas9 is used to knockout immune checkpoint genes (e.g., PD-1, TIGIT, LAG-3) in T cells, enhancing their anti-tumor activity by overcoming immunosuppressive effects in the GBM microenvironment." (PMID 40223940, 2025). "TIGIT binds to two different ligands, CD155 and CD112, which are expressed by tumor cells and antigen-presenting cells." (PMID 40075698, 2025). "TIGIT (T cell immunoreceptor with Ig and ITIM domains) is another inhibitory receptor co-expressed with PD-1 on tumor-infiltrating lymphocytes." (PMID 41584608, 2025). "In particular, two main ligands have been identified for TIGIT: CD112 (Nectin-2) and CD155 (poliovirus receptor, PVR), which are broadly expressed on antigen-presenting cells (APCs) and tumor cells." (PMID 40508202, 2025). "This unique tumor cluster exhibited high gene expression of 22 genes, including immune checkpoint regulators, like CTLA4, TIGIT, LAG3, and CD27, immune cell surface markers, and inflammatory genes." (PMID 40492347, 2025). "However, therapies targeting T cells (such as those which act on the PD1, LAG3 or TIGIT pathways) have yielded limited success in OC so far suggesting that other immune cells or other pathways might play a pivotal role in this type of tumor." (PMID 40464605, 2025). "Simultaneously, the high expression of immune checkpoint molecules like CTLA4 and TIGIT implies that Treg cells could establish an immunosuppressive state within the tumor microenvironment by suppressing the activation and proliferation of effector T cells, thereby facilitating tumor immune evasion." (PMID 41394809, 2025).
tumor (continued). "Along these lines, it was shown that a combination of blocking antibodies against TIGIT and PD-L1 or GD2 led to improved survival of NB tumour-bearing mice." (PMID 40317320, 2025). "Studies show that TIGIT and GITR regulate the functions of T cells and NK cells, while the VISTA and STING pathways boost the body’s anti-tumor responses." (PMID 40777027, 2025). "In the meantime, Plac1+ tumor cells shape a Treg‐related immunosuppressive microenvironment via CXCL11/CXCR3 and PVR/TIGIT, which in turn activates the tumorigenic signaling of Plac1+ tumor cells via LTA/LTBR and forms a reciprocal protumor loop." (PMID 40056047, 2025). "Co‐blockade of TIGIT with PD‐1, PD‐L1 or TIM‐3 has been highly effective in restoring the effector function of CD8+T cells in preclinical tumour models." (PMID 40415479, 2025). "The groundbreaking evolution of tumor immunotherapy has unveiled novel immune checkpoint molecules, such as TIM3, LAG-3, and TIGIT, heralding new possibilities for cancer immunotherapy." (PMID 40362568, 2025). "In the TIGIT signaling pathway network (TIGIT-NECTIN2 axis), tumor cells with a high CDI interacted with NK/T cells more significantly, which was conducive to tumor immunosuppression." (PMID 39773329, 2025). "TIGIT, which has the highest binding affinity for CD155, interacts with overexpressed CD155 on tumour cells." (PMID 41429765, 2025). "Several transcripts associated with immunological checkpoints, such as SIGLEC15, PDCD1LG2 (PD-L2), TIGIT, PDCD1 (PD-1), CD274 (PD-L1), CTLA4, LAG3, and HAVCR2 (TIM3), play a crucial role in tumor immune evasion." (PMID 40893939, 2025). "We injected CT26, 4T1 and B16F10 MMRd or MMRp cell lines in mice and used anti-TIM3/TIGIT/LAG3/CTLA4 alone or in combination with anti-PD-1, 14 days following tumor inoculation." (PMID 40027748, 2025). "Especially, a positive correlation between ACAA1 expression in tumor cells and six immune checkpoint-related genes, namely CD27, PDCD1, CD86, BTLA, TIGIT, and CD28, on immune cells within the tumor microenvironment." (PMID 41277949, 2025). "These nominated clusters upregulated key marker genes of activation, dysfunction, and differentiation that have been used to identify tumor specificity, such as CXCL13, TIGIT, PDCD1 (PD1), ENTPD1 (CD39), TOX, HAVCR2 (TIM-3), and LAG3." (PMID 40848148, 2025). "In these patients, the expression of TIM-3, TIGIT, PD-1, and CD39 on Vδ1 cells varied among PBLs, MALs, and tumor-infiltrating lymphocytes (TILs), depending on the tumor microenvironment." (PMID 40649775, 2025). "Our results revealed distinct patterns that vary between tumor types but globally resemble those of the Tex markers, and in some cases, they are expressed even higher than some Tex cell markers, like LAG3, PD1, TIGIT, and CXCL13." (PMID 40076932, 2025). "In vivo and in vitro experiments showed that VV-α-TIGIT significantly increased the recruitment and activation of T cells in the TME, leading to improved anti-tumor efficacy." (PMID 40821119, 2025). "Emerging reports suggest that inhibition of TIGIT(T cell immunoreceptor with Ig and ITIM domains) has shown promise in enhancing anti-tumor immunity by complementing the PD-L1/PD-1 axis." (PMID 40963868, 2025). "A significantly elevated expression of checkpoint inhibitors was detected in Cluster two tumours, including PD-1, PD-L1, CTLA4, CD80/CD86 costimulatory molecules, and emerging targets like TIGIT and LAG3." (PMID 41050056, 2025). "Here, we observed elevated co-expression of PD-1 with TIGIT, TIM-3, LAG-3, and NKG2A, which was particularly pronounced in tumor-infiltrating CD8+ T cells compared to peripheral blood." (PMID 41300994, 2025). "This strategy eliminated GSH and disrupted the TIGIT/PVR signaling axis, thereby strengthening the anti-tumor immune response and inhibiting tumor growth." (PMID 40403492, 2025).
tumor (continued). "CD155, an immune checkpoint molecule interacted with receptors of TIGIT/CD96/CD226 to exhibit co-inhibitory and co-stimulatory modulation on tumor immune microenvironment." (PMID 41181119, 2025). "TIGIT interacts with its ligands, CD155 (PVR) and CD112 (Nectin-2), which are often overexpressed on tumor cells and antigen-presenting cells (APCs) within the TME." (PMID 40567374, 2025). "Though single targeting of either TIGIT was able to partially ameliorate upregulation of exhaustion markers, dual targeting of TIGIT and CD73 was necessary to elicit robust tumor control." (PMID 38429294, 2024). "In consideration of M2 macrophages and Treg cells exhaust CD8+T cells in tumor immune microenvironment (TIME), we explored the correlation between several immune checkpoints expression (PD-1, TIM-3, CTLA-4, LAG3 and TIGIT) and TIBs in the TCGA database." (PMID 38762825, 2024). "In mouse tumor models, simultaneous inhibition of the TIGIT/PVR and PD-1/PD-L1 pathways improved anti-tumor activity compared with blockade of either pathway alone." (PMID 38451273, 2024). "Following successful CD8 and NK cell depletion, the delayed tumor growth conferred by anti-CTLA-4 and anti-TIGIT therapies was partially lost, suggesting that these responses are mediated by both CTLs and NK cells." (PMID 38914547, 2024). "ZGGS15 demonstrated a significant anti-tumor effect in the anti-PD-1 weak response model, outperforming single agents anti-LAG-3 or anti-TIGIT." (PMID 38724599, 2024). "Tumor cells express inhibitory molecules which interact with receptors on these TILs, like TIM-3, and TIGIT, inhibiting their activation and function." (PMID 39030523, 2024). "In the present study TIGIT and CD226 were expressed at higher levels by lymphocytes infiltrating CRC tumor tissues than adjacent, but the expression of CD155 was low or absent." (PMID 39113892, 2024). "Comparing immune cell infiltration in the peritumoral area and tumor core of glioblastomas showed that CD163+ cells were more abundant in the tumor core, similarly to the higher expression of the immunosuppressive markers PD-L1, IDO, and TIGIT." (PMID 38542199, 2024). "We found that it was correlated with tumor immunotherapy targets BTLA, CTLA4, HAVCR2, LAG3, PDCD1, and TIGIT in HNSC; ICOS were all significantly correlated." (PMID 39483471, 2024). "TIGIT and CD226 can compete for binding with CD155, and induce different immune responses in the tumor environment." (PMID 39113892, 2024). "An interesting study indicated that co-inhibition of PD1, TIGIT, and TIM3 led to the reactivation of tumor specific T cells." (PMID 38653982, 2024). "The transcriptomic profile that we found in tumour-reactive CD137+ CD8+ T cells suggested an exhausted/activated-like phenotype with increased expression of TNFRSF9, LAG3, PDCD1, TIGIT and HLA-DPA1/HLA-DQA1." (PMID 38986249, 2024). "TIGIT functions particularly strongly as a ligand for PVR and is highly expressed in tumor-infiltrating lymphocytes in many cancers, including endometrial, breast, renal cell, non-small cell lung, and colon cancer." (PMID 39156900, 2024). "TIGIT is overexpressed in multiple human cancers and strongly correlated with CD8 and PD-1 expression, particularly in tumor-infiltrating lymphocytes (TILs)." (PMID 38206370, 2024). "We report the generation of a novel anti-LAG-3/TIGIT bispecific IgG4 antibody, ZGGS15, and evaluated its anti-tumor efficacy in mouse models as monotherapy or in combination with a PD-1 antibody." (PMID 38724599, 2024). "Bispecific antibodies that simultaneously target PD1 and other inhibitory receptors like TIGIT, TIM3, or LAG3 are designed to reinvigorate these exhausted T cells, potentially restoring their anti-tumor functionality." (PMID 39591972, 2024). "The NK cell count was lower in peri-tumor liver specimens compared to ARLD, and an upregulation of TIGIT, an inhibitory marker, was observed in those peri-tumor specimens." (PMID 39944754, 2024).
tumor (continued). "In hPD-L1- and TIGIT-expressing murine colon cancer (MC38-HL1)-cell-grafted mice, the administration of P-O-T strongly inhibited tumor growth (55%)." (PMID 38257366, 2024). "Of note, anti-TIGIT immunotherapy prominently increased the CD90 and LGR5 expression in the tumor, which was markedly reversed by the addition of sulfarotene." (PMID 38543173, 2024). "Its co-expression with other immune checkpoint molecules (PD-1, TIGIT, and TIM3) results in T-cell exhaustion, a typical tumor immune escape mechanism." (PMID 38627681, 2024). "These infiltrating CD8+ lymphocytes have been primarily associated with inactivity and exhaustion given their constant exposure to tumor antigens and their high expression of inhibitory receptors such as PD-1, LAG-3, TIGIT, and CD39 46-48." (PMID 38250045, 2024). "The high expression of TIGIT is an essential indicator of the effectiveness of ICI treatment, with an adequate presence of tumor-infiltrating T cells in the TME serving as a prerequisite." (PMID 38711501, 2024). "TIGIT is overexpressed on tired TINK and tumor‐infiltrating T cells in different malignancies in peritumoral lymphocytes, always together with PD‐1 and TIM‐3, and is related to NK cell suppression and functional exhaustion." (PMID 38882209, 2024). "Performing cell-to-cell interaction and ligand-receptor analyses on spatial transcriptomics data they identified TIGIT expression on T and NK cells correlating with the expression of its ligands PVR and PVRL2 on myeloid and tumor cells." (PMID 38817612, 2024). "The results demonstrated a positive correlation between FANCD2 and immune checkpoints in most tumor tissues, including CTLA4, HAVCR2, LAG3, PDCD1, PDCD1LG2, SIGLEC15, TIGIT, and particularly CD274." (PMID 38443946, 2024). "Taken together, the data published so far demonstrate that CD155 induces an imbalance of TIGIT and DNAM-1 expression in the tumour microenvironment, further suppressing T-cell and NK cell activity, consequently promoting tumour growth and metastasis." (PMID 38893071, 2024). "During related mechanistic studies, it was found that there were more CD155 tumor cells and CD4+ CD25+ Tregs, with increased TIGIT levels following aspirin treatment." (PMID 39227959, 2024). "ZGGS15, a novel IgG4 BsAb that targets LAG-3 and TIGIT, has demonstrated exceptional anti-tumor efficacy by inhibiting LAG-3 and TIGIT." (PMID 38724599, 2024). "PVRL2 and PVR are predominantly expressed on tumor cells and antigen-presenting cells, binding to PVRIG and TIGIT, respectively, which are primarily found on T and NK cells, thereby suppressing antitumor immunity." (PMID 39156900, 2024). "We first constructed a tumor bearing model by subcutaneously injecting 4T1 cells into BALB/c mice, and treated them with anti-TIGIT mAb or IgG." (PMID 38216949, 2024). "We demonstrate that a high abundance of TILs co-expressing PD1 with LAG3, TIGIT, or TIM3 within the tumor microenvironment predicts poorer ORRs, PFS, and OS in patients with NSCLC treated with ICIs, regardless of PD-L1 status." (PMID 39591972, 2024). "Notably, addition of anti-TIGIT to anti-PD-L1 significantly reduced tumor growth and effectuated a trend of increased survival, while PD-L1 blockade by itself did not effectuate a clear survival benefit, possibly due to relatively low expression of PD-L1 in the tumor." (PMID 38181797, 2024). "In this context, cleavage of CD96, TIGIT, or DNAM1 in tumour-infiltrated lymphocytes cannot be excluded in response to TT." (PMID 38891113, 2024). "TIGIT/CD226 and CD96/CD226 gene expression ratios were substantially increased in tumor-infiltrating NK cells pre-treatment, indicating a disturbed balance shifted toward NK cell inhibition." (PMID 38181797, 2024). "For mouse modelling, we selected the syngeneic tumour model CT26, which has been used in previous studies of TIGIT antibody function and is infiltrated by T cells and myeloid cells at levels that are comparable to those in human NSCLC11–13." (PMID 38418879, 2024).